EGFR (epidermal growth factor receptor)
Diseases named in the same sentence as EGFR in open-access papers (continued):
Sharing a sentence is not in itself a finding about the gene and the disease.
lung cancer (continued). "Moreover, mitochondrial accumulation of EGFR induces mitochondrial fission through inhibition of mitofusin-1 protein and promotes cell migration and invasion in lung cancer." (PMID 30449278, 2018). "We tested 11 lung cancer cell lines - 8 with a KRAS or EGFR mutation and 3 with no known activating mutations in these genes – with a dosing strategy covering the previously determined active range of the drug." (PMID 30475204, 2018). "Also the prevalence of the RET fusions greatly increases (from a median 1.8% to a significative 6.3%) when evaluated in 159 lung cancer patients wild type for EGFR, ALK, ROS1, BRAF, KRAS, HER2." (PMID 29455670, 2018). "In addition, propolin C also inhibited EGF-induced migration and invasion as well as mesenchymal-like markers expressions in EGFR wild-type lung cancer cells." (PMID 29681982, 2018). "At this time, we are prospectively investigating the efficacy and safety of osimertinib for elderly patients ≥75 years old with ineffective prior EGFR-TKI treatment or with recurrence in EGFR-TKI mutation-positive and T790M mutation-positive nonsmall-cell lung cancer (NSCLC)." (PMID 29879078, 2018). "Indeed recently published clinical molecular guidelines in colorectal cancer recommend reporting to 5% VAF and lung cancer to 1% VAF with the ability to detect EGFR T790 in as few as 5% of cells." (PMID 29698444, 2018). "EMT phenotype has been connected to acquired EGFR TKI resistance in lung cancer patients." (PMID 29717264, 2018). "In conclusion, this study as well as our previous genetic studies on MTHFR in breast and prostate cancer, EGFR in lung cancer, and GPX-1 in bladder cancer is an important contribution in order to integrate pharmacogenetics in clinical practice in Ecuador and Latin America." (PMID 30065942, 2018). "The results will enhance our knowledge with respect to the contribution of EGFR SNPs to the development of lung cancer and may serve as potential genetic markers for predicting lung cancer risk." (PMID 30011810, 2018). "Due to the increased understandings of tumor biology and the signal pathways involved in lung cancer cells proliferation, several novel targeted agents that blocking dysregulated signaling pathways, such as EGFR and vascular endothelial growth factor (VEGF) pathways have been introduced." (PMID 29507704, 2018). "EGFR-Src-AKT signaling is required to maintain high Sox2 levels in lung cancer stem cells." (PMID 30060526, 2018). "The authors found concordance in the mutations of the key genes involved in lung cancer progression, such as cytokerain-8, cytokeratin-18, thyroid transcription factor 1 (TTF-1) and epidermal growth factor receptor (EGFR), both in expanded CTCs and primary tumors." (PMID 30586936, 2018). "Platinum-based chemotherapy is the recommended first-line treatment for the majority of advanced inoperable lung cancers, with the exception of inhibitors of epidermal growth factor receptor (EGFR) tyrosine kinase as the first-line therapy for patients with an activating EGFR mutation." (PMID 30344920, 2018). "Furthermore, repression of EMT-regulated migration and invasion was through downregulation of EGFR-mediated PI3K/Akt and ERK signaling pathways in EGFR-mutated HCC827 lung cancer cells." (PMID 29681982, 2018). "Furthermore, we demonstrated that EV-derived DNA is much more highly efficient for EGFR genotyping than cfDNA in lung cancer patients." (PMID 30526536, 2018). "Accordingly, EGFR is now an important target for lung cancer therapy." (PMID 29348400, 2018). "In the current study, we investigated whether lymph node metastases of lung cancer can be detected using the activatable method, by examining EGFR-positive lung squamous cell carcinoma in murine models." (PMID 29856819, 2018). "Increased EGFR expression was related to doxorubicin resistance in lung cancer cells." (PMID 30001383, 2018).
lung cancer (continued). "In this study, we found that CSE and its carcinogen B[α]P may render wtEGFR‐expressing lung cancer cells more insensitive to EGFR TKI through activation of the c‐MET/Akt signaling axis." (PMID 29570930, 2018). "Initial resistance might occur through the simultaneous activation of c-Met and EGFR pathways in lung cancer, whereas inhibiting both maximizes the inhibitory effect on the tumor." (PMID 29455668, 2018). "A distinct study in EGFR mutant lung cancer cell lines demonstrated that EGFR-specific TKIs engage a positive feedback loop involving induction of FGFRs and IL6, leading to STAT3 activation to promote cell survival and limit overall drug-induced growth inhibition." (PMID 29458371, 2018). "Also in EGFR mutant lung cancer cell lines, NFκB signaling was found to be rapidly induced upon EGFR inhibitor treatment to promote tumor cell survival and residual disease." (PMID 29458371, 2018). "However, these clinical results also demonstrated that the clinical impact of monotherapy with EGFR-directed agents in ESCC, even with EGFR amplification, differs from the dramatic responses seen in EGFR-mutant lung cancer." (PMID 28059068, 2017). "Similarly, in EGFR-TKI-resistant lung cancer cells with T790M mutation, the combination of a protein kinase CK2 inhibitor and an EGFR-TKI induced a high level of autophagy that degraded EGFR protein and promoted apoptosis." (PMID 28338617, 2017). "Most lung cancer cells expressed higher levels of EGFR than did normal cells." (PMID 28290155, 2017). "EGFR-mutant abundance has been recognized as a prognosis factor in lung cancer." (PMID 28076323, 2017). "Next, we examined whether EGFR signaling regulates miR-1 expression over time in lung cancer cells treated with EGF or EGFR inhibitor." (PMID 28537886, 2017). "Additionally, the recognized EGFR-mutant lung cancer cell line, NCI-H1975, conferred resistance to first-generation EGFR TKIs with mutation of T790M." (PMID 29072684, 2017). "Hence, understanding the molecular pathogenesis of lung cancer, particularly for the high levels of EGFR expression-related signaling and development of new therapeutic strategies will be of great significance in management of patients with lung cancers." (PMID 29152147, 2017). "However, dramatic clinical responses were demonstrated in patients with CNS metastases from lung cancer treated with the first-generation EGFR TKI icotinib in a recent phase III trial." (PMID 28784178, 2017). "Further, targeting EGFR and its family members using a combination of afatinib and cetuximab achieved improved therapeutic efficacies against acquired drug-resistant lung cancers with or without the EGFR T790M mutation." (PMID 29050315, 2017). "In Taiwan before 2011, neither the molecular testing for the EGFR mutation was routinely performed nor EGFR‐TKIs were approved as first‐line therapy for advanced lung cancer in the National Health Insurance (NHI) program." (PMID 28639751, 2017). "While the relationship between FDG uptake and EGFR mutations in NSCLC has previously been noted to have contradictory results, and one notable study has shown that the KRAS mutations in lung cancer showed significantly higher FDG uptake than wild type (WT) cancer." (PMID 28881771, 2017). "In vitro studies of EGFR-mutant lung cancer have shown that the expression of PD-L1 is increased in these cancer cells through downstream effectors in the EGFR pathway, such as STAT3 (signal transducer and activator of transcription 3) and ERK1/2 (extracellular signal-regulated kinase 1/2)." (PMID 29296194, 2017). "A better understanding of how Ref-1 effects the balance between cellular death and survival signals could lead to its use as a predictive marker for therapeutic response and resistance to EGFR-targeting treatments in lung cancer patients." (PMID 27935858, 2017).
lung cancer (continued). "In lung cancer, as well in other malignant carcinomas diseases, gene target-based therapies have emphasized the use of tyrosine kinase inhibitors (TKIs), focusing on a priority oncological gene target, the epidermal growth factor receptor (EGFR)." (PMID 28904641, 2017). "What’s more, it has a more specific relationship with lung cancer and has been proved to take part in the enhanced glutamine metabolism which could possibly be a surrogate marker to predict the respond to EGFR-TKIs." (PMID 29179454, 2017). "EGFR overexpression is correlated with the increased aggressiveness, metastases, and poor prognosis in various cancers, including head and neck cancer, colorectal cancer, pancreatic, lung cancer, renal cell, prostate carcinoma and malignant glioma." (PMID 28445134, 2017). "This case is exceptional, given the rarity of EGFR-mutant lung cancers in individuals with DS." (PMID 28903458, 2017). "The EGFR mutation was commonly observed in patients with family history of lung cancer compared to those not having the family history (χ2 p = 0.007)." (PMID 28486527, 2017). "EGFR oncogene is the most widely studied driver gene in lung cancer." (PMID 28784178, 2017). "We are interested in further determining whether miR-370 directly binds to the 3′UTR of the EGFR to understand the precise role and mechanisms in regulating the EGFR expression in lung cancer." (PMID 29152147, 2017). "Moreover, the usefulness of the inhibition of the HGF/Met pathway for the treatment of EGFR-TKI-resistant lung cancer cells has been reported." (PMID 28619066, 2017). "The aim of this study was to investigate whether the synthetic LXR agonist T0901317 can reverse EGFR‐TKI resistance of lung cancer cell lines A549 and H1650 and try to indentify its potential mechanism." (PMID 28097086, 2017). "Despite complicated collection methods and the requirement for technique-dependent platforms, it has generated substantial interest due, in part, to its potential to detect driver oncogenes such as epidermal growth factor receptor (EGFR) mutants in lung cancer." (PMID 28099915, 2017). "According to our review of the relevant literature, EGFR overexpression exceeds 90% in lung cancer." (PMID 28787001, 2017). "Given that the development of brigatinib is now in the late phase of clinical trials and anti-EGFR antibodies are now broadly used clinically for several cancers other than lung cancer, the findings of this study should help to overcome the acquired resistance to third-generation EGFR–TKIs." (PMID 28287083, 2017). "In this study, we found that metformin (Met), which is widely used for the treatment of type 2 diabetes (T2D), sensitized lung cancer cells bearing wild-type EGFR to Erlo treatment by enriching cancer cells expressing higher levels of EGFR with persistent phosphorylation." (PMID 29312591, 2017). "Because epithelial phenotype is less resistance to EGFR-TKIs, restoration of E-cadherin may increase the sensitivity of lung cancer cells to EGFR-TKIs." (PMID 28415568, 2017). "On that a probable connection between the efficacy of the EGFR-TKI-related therapy and overexpression of the lncRNA SOX2-OT and SOX2 protein has been associated with lung cancer cell proliferation and poor survival in a cohort that included 83 lung cancer patients." (PMID 28948003, 2017). "Inhibition of EGFR kinase activity using antibodies directed against the extracellular domain of EGFR (such as cetuximab) or small molecules that specifically inhibit the tyrosine kinase activity of EGFR (such as gefitinib) have emerged as alternative treatments for patients with lung cancer." (PMID 28290473, 2017). "Various EGFR alterations have been described in lung cancer." (PMID 29163769, 2017).
lung cancer (continued). "In recent years, kinase targeted therapies have been developed that have shown improved efficacy in treatment of lung cancer compared to standard chemotherapy, e.g., epidermal growth factor receptor (EGFR) tyrosine kinase inhibitors and anaplastic lymphoma kinase (ALK) inhibitors." (PMID 29371917, 2017). "Taken together, our data suggest that EGFR signaling might be involved in Pellino-1 upregulation in lung cancer but there is a possibility that another mechanisms are also involved." (PMID 28009353, 2017). "A549 and H332M human lung cancer cells are known to be resistant to TKIs because of the absence of mutations in EGFR on cell surface, whereas HCC827 human lung cancer cells contain mutated EGFR, thus are sensitive to TKIs." (PMID 29312591, 2017). "In the past decades, several biomarkers were discovered, for example, epidermal growth factor receptor (EGFR) in lung cancer patients and hormone receptor (HR), human epidermal growth factor receptor 2 (HER2), estrogen (ER), progesterone receptor (PR) in breast cancer patients." (PMID 29228627, 2017). "However, afatinib and the third-generation EGFR-TKIs, osimertinib and nazartinib, effectively inhibited the proliferation of these lung cancer cells." (PMID 29285266, 2017). "We found previously that integrinβ1-driven SRC activation is involved in enhanced cell migration and invasiveness as well as the acquisition erlotinib-resistance in human lung cancer cells harboring activated mutant EGFR, and integrinβ1 knockdown or inactivation overcomes drug resistance." (PMID 29050315, 2017). "In summary, we showed that lung cancer cell lines with EGFR mutations do not have high PD-L1 protein expression by an FDA approved PD-L1 test." (PMID 29119113, 2017). "Thus, the proportion of EGFR mutant tumors is somewhat higher in our study compared with general population in lung cancer patients." (PMID 29065153, 2017). "We also demonstrated that the MEOX2-GLI1 axis is clinically associated with poorer overall survival in lung cancer patients with both Epidermal Growth Factor Receptor (EGFR)-non-mutated and EGFR-mutated status." (PMID 28978016, 2017). "We have recently shown that gefitinib or osimertinib treatment results in the activation of not only STAT3, but also Src-YAP1 signaling, potentially operating downstream of IL-6, to promote cell survival and limit the initial response to EGFR TKI treatment in EGFR mutant lung cancer." (PMID 28521301, 2017). "Evidence also shows that miR-125a-5p may be as a potential tumor-suppressor in gastric cancer, and acts as an inhibitor to epidermal growth factor receptor signaling to block migration and invasion of lung cancer cells." (PMID 28580184, 2017). "The present study was undertaken to gain insight into the mechanism by which AQR could arise following the application of PI3K/mTOR inhibitors to EGFR inhibitor-refractory lung cancer." (PMID 29299135, 2017). "MiR-370 over-expression significantly reduced the EGFR 3′UTR-regulated luciferase activity, suggesting that miR-370 may bind to the 3′UTR of the EGFR to inhibit the EGFR expression in lung cancer cells." (PMID 29152147, 2017). "In conclusion, this is the first study to demonstrate that the presence of EGFR activating mutation is associated with better overall survival in NSCLC patients without family history of lung cancer." (PMID 28486527, 2017). "Next, gene fusion analysis was performed on RNA from FFPE tissue from 169 lung cancers in the prospective 533-sample cohort, which did not harbor mutations in EGFR, KRAS or BRAF (referred to as triple-negative cases hereon)." (PMID 28415793, 2017). "Put together, these results demonstrate that Met, which is widely used for the treatment of type 2 diabetes (T2D), sensitized lung cancer cells bearing wild-type EGFR to Erlo treatment by enriching cancer cells expressing higher levels of EGFR with persistent phosphorylation." (PMID 29312591, 2017).
lung cancer (continued). "Activation of AXL kinase has been associated with acquired resistance to EGFR kinase inhibitors in EGFR mutant lung cancer, with evidence for epithelial-to-mesenchymal transition in preclinical models and restored EGFR kinase inhibitor sensitivity upon AXL inhibition." (PMID 29050231, 2017). "With the discovery of oncogenic driver mutations in epidermal growth factor receptor (EGFR) and rearrangements in anaplastic lymphoma kinase (ALK) and ROS1, there has been a paradigm shift from a “one size fits all” approach to lung cancer treatment to more precise and rational targeted therapy." (PMID 28396848, 2017). "The activation of EGFR leads to the downstream phosphorylation of ERK in lung cancer cells." (PMID 28039459, 2017). "Taxanes antagonize the androgen receptor signaling pathway in prostate cancer cells by blocking dynein-mediated protein trafficking along interphase microtubules, and paclitaxel decreases the endocytic trafficking of epidermal growth factor receptor in lung cancer cells." (PMID 29246518, 2017). "In this study, we proposed that statins might enhance the effect of EGFR-TKIs and prolong survival in patients with lung cancer receiving EGFR-TKI therapy." (PMID 28158206, 2017). "These suggest that miR-370 may bind to the 3′UTR of EGFR mRNA and the miR-370 inhibitor in both lung cancer cells." (PMID 29152147, 2017). "In this study, we showed that the LXR agonist T0901317 could sensitize natural EGFR‐TKI‐resistant human lung cancer cell A549 to EGFR‐TKI." (PMID 28097086, 2017). "Also, EGFR tyrosine kinase inhibitors (TKIs) are under development and clinically used in for example lung cancer treatment." (PMID 28489591, 2017). "However, some lung cancer cells fail to respond to combined treatment with EGFR and MET inhibitors or develop resistance to dual EGFR/MET inhibition." (PMID 28420162, 2017). "In addition to the MEK/ERK signaling pathway, estrogen also activates the PI3K/AKT signaling pathway, another downstream pathway of the EGFR activation, to promote lung cancer cell metastasis through epithelial mesenchymal transition." (PMID 28783064, 2017). "ER and EGFR, as targets for dual lung cancer therapy, have been studied." (PMID 28783064, 2017). "Thus, EGFR expression in lung cancer cells has been explored for targeted gene delivery using nanoparticles." (PMID 28290155, 2017). "EGFR targeting drugs have also significantly improved the outcome of lung cancer patients." (PMID 28420162, 2017). "First, brigatinib did not demonstrate satisfactory efficacy in patients with EGFR-mutated lung cancer; a recent phase 1/2 trial reported that only two of 42 cases achieved partial response." (PMID 28287083, 2017). "Interestingly, we note that SCD1 reduction had less effect on cell proliferation under the condition of serum starvation, thereby implying that SCD1 is possibly dispensable for lung cancer growth when EGFR is inactivated." (PMID 28724430, 2017). "We next assessed whether YES is involved in the biological functions of EGFR-mutant lung cancer cells." (PMID 29163769, 2017). "We found that parental lung cancer cell lines harboring EGFR mutations showed negative (PC9 and H3255 cells) and positive (HCC827 cells) staining for PD-L1 by immunohistochemistry." (PMID 29119113, 2017). "EGFR and its downstream signaling pathways involving MEK/ERK, p38 MAPK, and PI3K/Akt play key roles in the proliferation and differentiation of normal epithelial cells and has been associated with the development of tumor, especially lung cancer." (PMID 28160565, 2017).